GPC1 (glypican 1)
Diseases named in the same sentence as GPC1 in open-access papers (continued):
Sharing a sentence is not in itself a finding about the gene and the disease.
pancreatic cancer (continued). "Among 60 specimens of pancreatic cancer, 3 cases (5%) showed high GPC1 expression (IHC score of +3), 56 cases (93%) showed low to intermediate levels of staining (IHC scores of +1 or +2), and no immunoreactivity was observed in 1 case (2%)." (PMID 37031249, 2023). "To evaluate the involvement of GPC1 in Wnt signaling in pancreatic cancer cells, we determined the expression of Wnt3a." (PMID 37031249, 2023). "Although they bound to GPC1 expressed on T3M4 pancreatic cancer cell line with similar affinity, the HM2 clone was chosen for the following studies as it showed the highest protein production yield among all the mAbs." (PMID 37031249, 2023). "For instance, exosomes, glypican-1 (GPC1), are sensitive indicators for identifying early pancreatic cancer lesions." (PMID 37689664, 2023). "In pancreatic cancer, GPC1 expression is observed not only in cancer cells but also in cancer-associated fibroblasts of the stroma." (PMID 37827841, 2023). "Previous study in pancreatic cancer identified that exosomes released from tumor contained a membrane bound protein called GPC1, considered as a sensitive and unique biomarker in early-stage disease." (PMID 37875600, 2023). "GPC1 antibody conjugated with monomethyl auristatin E is delivered to the GPC1-expressing CAFs, leading to apoptosis of surrounding pancreatic cancer cells." (PMID 35159011, 2022). "CA19-9 serum levels cannot distinguish patients with intraductal papillary mucinous tumors (PCPL) from healthy controls, while GPC1-positive serum exosomal had 100% sensitivity and specificity in all stages of pancreatic cancer (e." (PMID 36119470, 2022). "In recent years, serum GPC-1+ exosomes have received much research interest in the diagnosis of early-stage pancreatic cancer." (PMID 36313694, 2022). "Serum exosomal GPC-1 was significantly elevated in patients with pancreatic tumors compared with HCs, especially in PDAC." (PMID 36313694, 2022). "For example, 100% of exosomes from individuals with pancreatic cancer show glypican-1 (GPC1+) expression compared with only 2.3% in healthy individuals." (PMID 35664698, 2022). "The level of GPC1+ circulating exosomes was shown to distinguish healthy subjects and patients with benign pancreatic disease from patients with early- and late-stage pancreatic cancer." (PMID 36109501, 2022). "Circulating EVs with GPC1 (GPC1+Exos) have been isolated from the blood of 250 pancreatic cancer patients, which distinguished patients with chronic pancreatitis from those with pancreatic cancer (early and advanced stages)." (PMID 36407096, 2022). "GPC1 protein expression levels are high in pancreatic cancer, squamous cell carcinoma of the esophagus, prostate cancer, breast cancer, and gliomas." (PMID 36142190, 2022). "The expression of GPC1 in pancreatic cancer is very high, and it is also involved in the proliferation and the metastasis of tumor cells." (PMID 36295924, 2022). "GPC1 is upregulated in pancreatic cancer, esophageal cancer, and prostate cancer, and it promotes the proliferation and movement of esophageal cancer cells by PTEN/Akt/β-catenin pathway." (PMID 35233466, 2022). "For example, GPC1, the same subfamily gene of GPC2, has been proved to be a diagnostic biomarker and therapeutic target for pancreatic cancer and trigger a wave of interest of glypicans." (PMID 35345673, 2022). "Similar to Colorectal Cancer, the cell surface proteoglycan Glyptican1 (GPC1) is the most prominent biomarker of pancreatic cancer." (PMID 36032679, 2022). "GPC-1 combined with EpCAM has been found to differentiate sEVs derived from pancreatic cancer or normal pancreatic epithelial cells with 90% accuracy." (PMID 36167539, 2022). "In pancreatic cancer cell lines, GPC1 plays a key role in the mitogenic stimuli provided by fibroblast growth factor 2 (FGF2) and heparin-binding EGF-like growth factor (HB-EGF)." (PMID 36142190, 2022).
pancreatic cancer (continued). "As GPC1 also has a secreted soluble form, it has been reported to be detected in serum exosomes and is promising for the early detection of pancreatic cancer." (PMID 36158119, 2022). "Treatment with GPC1 antibody conjugated with microtubule inhibitor monomethyl auristatin E inhibits pancreatic cancer in a pancreatic tumor xenograft mouse model." (PMID 35159011, 2022). "A recent study also showed that pancreatic tumor cells produce exosomes indicating surface marker glypican-1, which were identified in blood samples from pancreatic cancer patients." (PMID 35159299, 2022). "One study showed that exosomes derived from pancreatic cancer cells were enriched with a proteoglycan, glypican 1 (GPC1), on the surface of the parental cells." (PMID 35501802, 2022). "Exosomes enriched in GPC1 are known to positively regulate cancer and thereby serve as the best biomarker for detecting pancreatic cancer." (PMID 36032679, 2022). "Pancreatic cancer patients exhibit higher GPC1+ circulating exosomes than in healthy donors, and elevated level of GPC1+ circulating exosomes is also observed in Ptf1a-Cre; lox-stop-lox-KrasG12D/+; Tgfbr2lox/lox mice." (PMID 35159011, 2022). "The presence of GPC1+ exosomes distinguished healthy subjects and patients with a benign pancreatic disease from patients with early-stage pancreatic cancer." (PMID 35501802, 2022). "For instance, GPC1, a cell surface proteoglycan is overexpressed in breast and pancreatic cancers and only detected in EVs derived from these malignant cells." (PMID 36407096, 2022). "In another cohort including 192 patients and 100 healthy donors, GPC-1 + sEVs distinguished patients with benign pancreatic disease from those in different stages of pancreatic cancer with high specificity and sensitivity." (PMID 36167539, 2022). "After intrapancreatic injection of PANC-1 or T3M4 (human pancreatic cancer cell line), decreased angiogenesis and metastasis were observed in GPC1-null athymic mice compared with GPC1-positive athymic mice." (PMID 36142190, 2022). "Knockdown of GPC1 in the human pancreatic cancer cell line PANC-1 resulted in a reduction in tumor growth, metastasis, and angiogenesis compared to the PANC-1 cell line without knockdown." (PMID 36142190, 2022). "The proportion of GPC1+ EVs is higher in patients with advanced pancreatic cancer, which decreases following regional intra-arterial chemotherapy treatment." (PMID 35501802, 2022). "They reported that GPC1+ circulating sEVs were detected in sera of pancreatic cancer patients with high sensitivity and selectivity." (PMID 36499561, 2022). "A few studies stemmed from the finding that GPC1 identifies cancer exosomes and detects early pancreatic cancer." (PMID 34249755, 2021). "GPC1, for instance, when upregulated, increases tumour angiogenesis and metastasis in pancreatic cancer." (PMID 33494442, 2021). "In cancer research, Glypican-1 (GPC1) in exosomes effectively helped to identify pancreatic cancer patients." (PMID 33869195, 2021). "GPC1 overexpressed on serum-derived sEVs has extremely high sensitivity and specificity in prediction of pancreatic cancer." (PMID 34094979, 2021). "GPC-1 positive exosomes enabled distinguishing healthy individuals from those with early and late stage pancreatic cancer and from those with benign pancreatic disease." (PMID 33968983, 2021). "In this report, one novel method has been developed to screen the monoclonal antibody against human pancreatic cancer biomarker glypican-1 (GPC1) through the combination of fluorescent cell sorting and single B cell amplification." (PMID 34527051, 2021). "The authors presented that the FGF2-growth factor-induced shedding of syndecan-1 from the cell membrane makes the mitogenic response of pancreatic cancer cells glypican-1 dependent, which in turn cannot be compensated for by syndecan-1." (PMID 33742285, 2021).
pancreatic cancer (continued). "It has been described as an activator of KRAS and glypican-1 in pancreatic cancer and, very recently, it was reported in relation to acinar cell-derived tumorigenesis." (PMID 33762742, 2021). "From these important observations, GPC1 has been considered druggable as a marker and/or a targeted drug for pancreatic cancer." (PMID 34249755, 2021). "Studies related to pancreatic cancer biomarkers are more complementary; glypican-1 (GPC1), MIF, EGFR are all used to successfully diagnose patients with healthy controls." (PMID 34336803, 2021). "The successful application of GPC1 mRNA detection in EVs indicates its potential to facilitate early detection of pancreatic cancer." (PMID 34565398, 2021). "Other studies have evaluated the feasibility of various chimeric antigen receptor (CAR)-modified T cells recognising antigens such as mesothelin and glypican-1 in solid tumours including pancreatic cancer." (PMID 33917882, 2021). "Glypican‐1 (GPC1), a cell surface proteoglycan, was found to enrich circulating EVs (crEVs) in pancreatic cancer patients, and GPC1‐positve crEVs levels are predictive of disease‐specific survival." (PMID 33145869, 2021). "Gold nanoparticles have been decorated with an anti-glypican-1-antibody and used for specific detection of pancreatic cancer." (PMID 34249755, 2021). "Recently, a promising early-stage pancreatic cancer biomarker, extracellular vesicles (EVs) related glypican-1 (GPC1) mRNA, is found to overexpress in pancreatic cancer cells." (PMID 34565398, 2021). "Exosomal GPC1 was significantly related to tumor burden and the survival of patients because it distinguishes healthy people from pancreatic cancer patients." (PMID 34595207, 2021). "Among them, PD-L1 mediated tumor immune escape and immunotherapy resistance; Integrins promote specific metastasis of some tumors; GPC1, a biomarker of pancreatic cancer and CRC, accelerates the progression of CRC." (PMID 34094979, 2021). "In facts, GPC1-targeted and gemcitabine-loaded liposomes efficiently reduced tumor burden in a orthotopic pancreatic cancer (PDAC) mice." (PMID 34249755, 2021). "For instance, exosomal levels of glypican 1 (GPC-1), proteoglycan, in the blood was assessed for detection of pancreatic cancer." (PMID 33968983, 2021). "The abundance of GPC1 also positively correlates with disease severity of pancreatic cancer patients, independently on surgical treatment, suggesting that GPC1 is a surgery-independent diagnostic biomarker." (PMID 33494442, 2021). "Glypican-1 (GPC1), for instance, as a cell surface proteoglycan, is specifically expressed by exosomes isolated from the serum of pancreatic cancer patients, and it is used as an early biomarker." (PMID 34917064, 2021). "Glypican-1(GPC-1) is a potential biomarker for pancreatic cancer diagnosis, and human leucine rich alpha-2-glycoprotein 1 (LRG1) in urinary sEVs is a potential biomarker for diagnosis of NSCLC." (PMID 34685415, 2021). "Blood exosomes from patients with pancreatic cancer (n=24), pancreatitis (n=29) and other cancers (n=20) were analyzed by flow cytometry for exosomal GPC1 and CD82 and serum CA19-9." (PMID 34249755, 2021). "Glypican 1 (GPC1) levels on pancreatic cancer-derived sEVs indicated cancer burden in patients before and after surgery, exhibiting significant diagnostic and predictive potentials." (PMID 33791224, 2021). "Further, it has been reported that levels of GPC1+ exosomes are correlated with pancreas tumor burden and survival rate." (PMID 34917064, 2021). "GPC1 is overexpressed in human pancreatic cancer cells, breast cancer cells, and gliomas, and it increases the proliferative response to FGF2, heparin-binding epidermal growth factor-like growth factor (HBEGF), and HGF." (PMID 33606708, 2021).
pancreatic cancer (continued). "Although no EV-based biomarkers are currently used for diagnostic or prognostic purposes, there are multiple studies assessing the clinical use of EVs in cancer, including a clinical trial of Gylpican-1+ (GPC1+) EVs for the diagnosis of pancreatic cancer." (PMID 34069860, 2021). "They concluded that patients with advanced pancreatic cancer who displayed a decrease in GPC1+ EVs experienced enhanced overall survival rates with the aid of RIAC therapy." (PMID 33672926, 2021). "At last, we used EVs related GPC1 mRNA as a target, and this platform successfully identified the pancreatic cancer cell line (AsPC-1)." (PMID 34565398, 2021). "The most cited article was “Glypican-1 identifies cancer exosomes and detects early pancreatic cancer”, written by Sonia A. Melo, published in “Nature”, and cited 1561 times." (PMID 34898576, 2021). "For instance, in the case of pancreatic cancer Glypican-1+ EVs were found in patients, and the levels of these particles were even higher in patients with distant metastases." (PMID 34360924, 2021). "GPC1 was proven to distinguish healthy individuals and patients with a benign pancreatic disease from patients with early- and late-stage pancreatic cancer." (PMID 33494442, 2021). "They observed that GPC1-positive circulating exosomes were specifically and sensitively detectable in the serum of patients with pancreatic cancer." (PMID 33803776, 2021). "Several studies have reported the utility of glypican-1 (GPC1)-positive exosomes in the diagnosis of pancreatic cancer 38-40." (PMID 33613112, 2021). "In recent years, extracellular vesicles (EVs) with high glypican-1 (GPC1) expression level have been regarded as effective potential biomarkers for pancreatic cancer diagnosis." (PMID 34565398, 2021). "In particular, GPC1, which was expected to be expressed low in pancreatic cancer, was actually highly expressed in EVs." (PMID 34948417, 2021). "GPC1 is a membrane-anchored protein overexpressed in multiple tumors and involved in the tumorigenesis of certain cancers, including breast cancer and pancreas cancer." (PMID 33747908, 2021). "The scientific literature is robust regarding how either GPC1 or other GPCs positively regulate cellular proliferation in pancreatic cancer, esophageal squamous cell carcinoma, rhabdomyosarcoma, hepatocellular carcinoma, and liver cancer." (PMID 32180897, 2020). "Another interesting study identifies glypican-1 (GPC1) as a biomarker of early state pancreatic cancer." (PMID 32041096, 2020). "GPC1 is suitable to differentiate early- and late-stage pancreatic cancer from benign diseases of the pancreas, with an accuracy of 100%." (PMID 32731530, 2020). "Glypican 1 (GPC1) was used to isolate TEX from plasma of patients with pancreatic cancer, and prostate-specific membrane antigen (PSMA) was used to isolate TEX from plasma of prostate cancer patients." (PMID 32709086, 2020). "Glypican 1 is widely expressed in pancreatic cancer, glioma, and breast carcinoma, and low levels of glypican 1 inhibit metastasis, growth, and tumorigenicity." (PMID 32478377, 2020). "A cell growth assay with ADCs was performed using the GPC-1-positive pancreatic cancer cell lines BxPC-3 and T3M-4." (PMID 32152502, 2020). "Glypican 1 (GPC1) expression in blood exosomes of pancreatic cancer patients was able to distinguish patients with benign or malign disease with absolute specificity and sensitivity." (PMID 32197468, 2020). "For example, one study tested cell surface proteoglycan, glypican-1 (GPC1) on serum exosomes in patients harbouring pancreatic cancer at both pre-and post-operative levels." (PMID 32854710, 2020). "Our preclinical data demonstrated that targeting GPC-1 by ADC is a promising therapy for patients with GPC-1-positive pancreatic cancer." (PMID 32152502, 2020). "Our preclinical data demonstrated that targeting GPC-1 with ADC is a promising therapy for patients with GPC-1-positive pancreatic cancer." (PMID 32152502, 2020).
pancreatic cancer (continued). "We analysed the relation between GPC-1 expression in pancreatic cancer and various clinicopathological parameters, and found the correlation between high expression of GPC-1 and lymph node metastasis." (PMID 32152502, 2020). "In pancreatic cancer cells, GPC1 interaction with TGF-β1 promotes SMAD pathway activation resulting in cell growth inhibition." (PMID 32916872, 2020). "Among other proteoglycans, Glypican-1 (GPC1) has been found on the exosomes formed by pancreatic cancer cells and was suggested to be a useful indicator of the early stages of this cancer." (PMID 32629890, 2020). "Exosomes isolated from pancreatic cancer patient serum were enriched in glypican-1, a useful biomarker for predicting pancreatic cancer." (PMID 32992699, 2020). "We also assessed the antitumour efficacy of GPC-1-ADC against a pancreatic cancer patient tumour-derived xenograft (PDX)." (PMID 32152502, 2020). "GPC1 significantly affects the growth of pancreatic cancer cells in vivo and significantly attenuates tumor angiogenesis and metastasis in athymic mice." (PMID 32744303, 2020). "Regarding pancreatic cancer, Kalluri and colleagues found that glypican-1 (GPC1), a cell surface proteoglycan, is specifically enriched in circulating exosomes (30–200 nm endosome-derived EVs)." (PMID 32731530, 2020). "Nevertheless, GPC1 appeared specifically enriched in circulating pancreatic cancer cell-derived exosomes." (PMID 32974169, 2020). "For example, inhibition of GPC-1 in PANC-1 pancreatic cancer cells decreased the ability of these cells to form tumors in nude mice." (PMID 31391540, 2019). "At 65 days of age, 14 of 14 animals harboring wild type GPC1 developed large pancreatic tumors that invaded the surrounding organs, whereas 16 of the 20 GPC1−/− mice developed smaller and non-invasive tumors." (PMID 31681616, 2019). "Compared with healthy individuals, the levels of GPC-1+ EVs were significantly increased in patients with advanced pancreatic cancer." (PMID 31355137, 2019). "To validate the use of GPC1+ve EVs for screening and detection of pancreatic cancer, we utilized nanoscale flow cytometry which is an instrument specialized for high-throughput and multi-parametric analysis of Evs." (PMID 30800217, 2019). "It was demonstrated that the utilization of GPC1+ exosomes led to the successful detection of early stages of pancreatic cancer and to the differentiation between patients with different stages of progression of this cancer." (PMID 31096692, 2019). "Both of their signaling were inhibited after GPC-1 was knocked down in a mouse model of pancreatic cancer." (PMID 31355137, 2019). "While GPC1 was unable to discern pancreatic cancer from BPD, nFC technology opens up the possibility of the re-examining previously-identified pancreatic cancer markers in novel combinations to develop an effective early detection test for pancreatic cancer." (PMID 30800217, 2019). "For example, Exo containing Glypican-1 (GPC1) is very sensitive and specific biomarkers of pancreatic cancer in blood of patients." (PMID 31281356, 2019). "We tested the utility of a blood test enumerating EVs positive for the pancreas-specific marker Glycoprotein 2 (GP2) and the putative pancreatic cancer marker Glypican-1 (GPC1) in patients with PDAC." (PMID 30800217, 2019). "GPC1 is a pan-specific marker for cancer that is not only elevated in pancreatic cancer, but is also elevated in other neoplastic diseases, such as breast cancer and gliomas." (PMID 30800217, 2019). "GPC1-positive exosomes have been employed to detect pancreatic cancer, while circulating exosomal macrophage migration inhibitory factor (MIF) was able to predict liver metastasis onset." (PMID 31537986, 2019). "The ROC curve further demonstrates the ineffectiveness of GPC1 EVs and GPC1+GP2 EVs in discerning BPD from pancreatic cancer." (PMID 30800217, 2019).